SRPK2 (SRSF protein kinase 2)
Description:
Serine/arginine-rich protein-specific kinase which specifically phosphorylates its substrates at serine residues located in regions rich in arginine/serine dipeptides, known as RS domains and is involved in the phosphorylation of SR splicing factors and the regulation of splicing. Promotes neuronal apoptosis by up-regulating cyclin-D1 (CCND1) expression. Phosphorylates ACIN1, and redistributes it from the nuclear speckles to the nucleoplasm, resulting in cyclin A1 but not cyclin A2 up-regulation. Plays an essential role in spliceosomal B complex formation via the phosphorylation of DDX23/PRP28. Probably by phosphorylating DDX23, leads to the suppression of incorrect R-loops formed during transcription; R-loops are composed of a DNA:RNA hybrid and the associated non-template single-stranded DNA. Can mediate hepatitis B virus (HBV) core protein phosphorylation. Plays a negative role in the regulation of HBV replication through a mechanism not involving the phosphorylation of the core protein but by reducing the packaging efficiency of the pregenomic RNA (pgRNA) without affecting the formation of the viral core particles. Phosphorylates the N-terminus of ERC1 (By similarity).
Synonyms: SFRSK2
Tractability: Small molecule: a structure with a bound ligand is known; a high-quality ligand is known; it has a high-quality binding pocket; it belongs to a druggable protein family. PROTAC: ubiquitination databases record sites on it; its protein half-life has been measured; a small molecule that binds it is known.
Target class: CMGC protein kinase group; Enzyme; Kinase; Protein Kinase; CMGC protein kinase SRPK family
Chemical probes: JH-XI-05-01 (high quality), MSC1186 (high quality)
Gene: Protein-coding gene on chromosome 7 (105,110,704 to 105,399,308, reverse strand). Ensembl gene ENSG00000135250.
Subcellular location: Cytoplasm; Nucleus, nucleoplasm; Nucleus speckle; Chromosome
Subcellular location (Human Protein Atlas): Cytosol; Nucleoplasm; Acrosome; End piece; Nucleoli
Pathways (Reactome):
Disease: Maturation of nucleoprotein
Gene Ontology:
Molecular function: ATP binding; magnesium ion binding; protein binding; protein serine kinase activity; protein serine/threonine kinase activity; RNA binding; 14-3-3 protein binding; protein kinase activity
Biological process: intracellular signal transduction; negative regulation of viral genome replication; peptidyl-serine phosphorylation; positive regulation of cell population proliferation; positive regulation of viral genome replication; protein phosphorylation; R-loop processing; RNA splicing; spliceosomal complex assembly; angiogenesis; innate immune response; nuclear speck organization; phosphatidylinositol 3-kinase/protein kinase B signal transduction; positive regulation of cell cycle; positive regulation of gene expression; positive regulation of neuron apoptotic process; regulation of mRNA processing; regulation of mRNA splicing, via spliceosome; regulation of gene expression
Cellular component: chromatin; chromosome; cytoplasm; cytosol; nuclear speck; nucleolus; nucleoplasm; nucleus; presynapse
Genetic constraint (gnomAD): Loss-of-function variants: 18 observed, 76.98 expected, observed/expected ratio (o/e) 0.23, 90% interval 0.16 to 0.35. The upper end of that interval is the gene's LOEUF score, 0.35, which puts it in group 1 of 6, group 1 being the genes least tolerant of losing a copy. Missense variants: 600 observed, 851.79 expected, observed/expected ratio (o/e) 0.7, 90% interval 0.66 to 0.75. Synonymous variants: 275 observed, 313.14 expected, observed/expected ratio (o/e) 0.88, 90% interval 0.8 to 0.97.
Homologues: Orthologues: chimpanzee SRPK2 (99% identical), macaque SRPK2 (96% identical), pig SRPK2 (94% identical), rabbit SRPK2 (94% identical), dog SRPK2 (93% identical), rat Srpk2 (92% identical), guinea pig SRPK2 (91% identical), mouse Srpk2 (91% identical), tropical clawed frog srpk3 (83% identical), Drosophila melanogaster SRPK (45% identical), Caenorhabditis elegans spk-1 (44% identical), Drosophila melanogaster CG8565 (33% identical), and 10 more. Paralogues in human: SRPK1 (57% identical), SRPK3 (51% identical), NLK (15% identical), MAPK10 (14% identical), CILK1 (14% identical), MAPK8 (14% identical), MAPK9 (14% identical), MAPK14 (14% identical), MAPK7 (14% identical), MAK (13% identical), MAPK11 (13% identical), MAPK13 (13% identical), and 7 more.
Diseases named in the same sentence as SRPK2 in open-access papers:
SRPK2 is named in the same sentence as 48 diseases in open-access papers, as found by Europe PMC text mining. Sharing a sentence is not in itself a finding about the gene and the disease. The quoted sentences say what the papers report.
leukemia (7 papers, 2015 to 2025). A malignant (clonal) hematologic disorder, involving hematopoietic stem cells and characterized by the presence of primitive or atypical myeloid or lymphoid cells in the bone marrow and the blood. "SRPK2 is less well studied, but there is evidence that it is also involved in cancer including leukaemia." (PMID 36895328, 2023). "Previous investigations have described the overexpression of SRPK1 and SRPK2 in leukemia and other cancer types, suggesting that they would be useful targets for developing novel antitumor strategies." (PMID 26244849, 2015). "In leukemia cells, SRPK2 overexpression leads to hyperphosphorylation of the splicing factor acinus, which in turn is responsible for increasing the transcription level of cyclin A1 and affecting cell proliferation." (PMID 26244849, 2015). "In leukemia, SRPK2 overexpression has been shown to result in increased cell proliferation due to SR protein acinus phosphorylation and cyclin A1 upregulation." (PMID 26273588, 2015). "SRPK1 and SRPK2 have been found overexpressed in different types of cancer including breast, colon, pancreatic carcinomas, leukemia, nonsmall cell lung carcinoma, squamous cell lung carcinoma, gliomas, ovary, and hepatocellular carcinoma." (PMID 26273588, 2015). "Taken together, these results demonstrate that the expression of SRPK1 and SRPK2 are proportionally distinct among the leukemia cells analyzed." (PMID 26244849, 2015). "In addition, SRPK2 is overexpressed in several cancer types, including leukemia and lung, colon, prostate and pancreatic cancers." (PMID 31898732, 2020). "Considering this structural similarity, the position of the ATP analog, previously co-crystallized with SRPK1, allowed the prediction of its binding site into SRPK2, the paralog chosen to be studied herein, because its mechanisms in leukemia tumorigenesis have been previously well determined." (PMID 26244849, 2015). "To expand previous findings and gain further information about the relative proportion between SRPK1 and SRPK2 expression among the leukemia cells used in this work, we evaluated the expression of SRPK1 and SRPK2 in a panel of leukemia cell lineages from different origins and genetic backgrounds." (PMID 26244849, 2015). "Based on these accumulated SRPK1 and SRPK2 gene expression data, we aimed to investigate the cytotoxic effect of the SRPK inhibitor SRPIN340 on leukemia cells." (PMID 26244849, 2015). "SRPK2 promoted the cell proliferation of leukemia by regulating cyclin A1 (not cyclin A2) expression." (PMID 31898732, 2020).
Alzheimer disease (5 papers, 2018 to 2024). A progressive, neurodegenerative disease characterized by loss of function and death of nerve cells in several areas of the brain leading to loss of cognitive function such as memory and language. "On the other hand, SRPK2 has been widely linked to AD (Alzheimer’s disease) by phosphorylating tau, a neuronal microtubule-associated protein, and inducing its polymerization, thus leading to supression of tau-dependent microtubule polymerization, and inhibiting axonal elongation in neurons." (PMID 37907504, 2023). "In the context of Alzheimer’s disease, legumain phosphorylation at S226 by SRPK2 led to accumulation of cytoplasmic legumain, promoting cleavage of tau, APP, and SRPK2 itself." (PMID 38199506, 2024). "Furthermore, 14-3-3 proteins interact with serine-arginine protein kinase 2 (SRPK2) and prevent the formation of hyperphosphorylated tau in Alzheimer’s disease." (PMID 37630190, 2023).
prostate carcinoma (5 papers, 2020 to 2025). A carcinoma that arises from epithelial cells of the prostate gland. "Then, we evaluated the gene expression profiles for the six HUB nodes (ABL1, EP300, FYN, MYC, PSMB2, and SRPK2) in all the prostate cancer cells, compared to normal prostate EPN cells." (PMID 32933107, 2020). "In addition to SRPK1, another member of SRPKs, SRPK2, is suggested to promote the growth and metastasis of prostate cancer, although SRPK2 targets associated with these phenomena have not been identified." (PMID 32106418, 2020). "SRPK2 (Serine/Arginine-Rich Protein-Specific Kinase-2, SRSF protein kinase-2) is up-regulated in multiple human tumors, and plays an important role in the progression and metastasis of prostate cancer." (PMID 35178295, 2022). "Moreover, SRPK2 and PSMB2 over-expression was observed in prostate cancer, and correlated with a high Gleason score, advanced pathological stage, tumor metastasis, and significantly poor 10-year metastatic rate in prostate cancer, in younger men." (PMID 32933107, 2020).
breast carcinoma (4 papers, 2021 to 2025). "Knockdown of serine/arginine-rich protein-specific kinase 2 (SRPK2) resulted in an impairment of de novo lipogenesis similar to the phenotype observed in breast cancer cells with OGT depletion." (PMID 37838167, 2023). "In breast cancer cells, SRPK2 is modified with O-GlcNAc at its nuclear localization sequence, which enhances the binding of SRPK2 to importins, thus increasing nuclear translocation of SRPK2, independent of SRPK2 mTORC1/S6K1 phosphorylation." (PMID 37838167, 2023). "At a six-hour time point, there was a substantial increase in nuclear SRPK2 upon IGF-1 exposure in both breast cancer cell lines, which was abrogated upon rapamycin treatment." (PMID 36096767, 2022). "We further investigated the subcellular localization of phosphorylated SRPK2 upon IGF- 1 exposure by performing cell fractionation in which breast cancer cells were treated with a vehicle or rapamycin and exposed to IGF-1." (PMID 36096767, 2022). "Thus, we aimed to determine if the IGF-1-mTORC1 axis affects the subcellular localization of SRPK2 in breast cancer cells." (PMID 36096767, 2022). "Upon SRPK2 knockdown and inhibition, we observed a decrease in FASN protein and mRNA stability, respectively, in response to IGF-1 exposure that was specific to triple negative and HER2+ breast cancer cell lines." (PMID 36096767, 2022). "Surprisingly, we observed a specific decrease in FASN protein expression upon SRPK2 knockdown only in the MDA-MB-231 breast cancer cells and not int the MCF-7 cells." (PMID 36096767, 2022). "Additionally, SRPK1 and SRPK2 showed upregulated expression in CAC tissues compared with adjacent tissues, which is consistent with their expression patterns in acute myeloid leukemia, breast cancer, and pancreatic cancer." (PMID 33602301, 2021).
pancreatic cancer (4 papers, 2020 to 2025). "Whether SRPK2 affects the expression of Numb in pancreatic cancer may be worth studying in the future." (PMID 35345586, 2022).
colorectal cancer (2 papers, 2020 to 2022). A primary or metastatic malignant neoplasm that affects the colon or rectum. "Serine-arginine protein kinase 2 (SRPK2) is aberrantly expressed in human malignancies including colorectal cancer (CRC)." (PMID 31898732, 2020). "Most recently, SRPK2 expression was shown to be higher in colorectal cancer tumors compared to nontumor tissues, and was positively associated with tumor differentiation, primary tumor (T) stage, regional lymph nodes (N) stage, and UICC stage." (PMID 35463320, 2022).
COVID-19 (2 papers, 2022 to 2024). A disease caused by infection with severe acute respiratory syndrome coronavirus 2. "After adjusting for confounding factors, CST5, NADK, SRPK2 and TGF-α were differentially detected in COVID-19 and non-COVID-19 patients." (PMID 35967328, 2022). "CST5 (adjusted fold change (FC)=0.065, p value<0.001), SRPK2 (adjusted FC=0.664, p value=0.003) and TGF-α (adjusted FC=0.647, p value=0.026) showed lower levels in COVID-19 patients." (PMID 35967328, 2022).
Intellectual disability (2 papers, 2020 to 2023). "SRPK2 deletions and SRPK3 point mutations have been identified in intellectual disability patients, which are predicted to disrupt SRPK kinase activity and downstream signalling." (PMID 37607329, 2023). "Interestingly, the discovery of SRPK2 heterozygous deletions and SRPK3 amplifications associated with intellectual disability suggests that gene dosage is critical for correct regulation of SRPK signalling." (PMID 37607329, 2023). "Therefore, we propose that SRPK2 deletion or SRPK3 mutation may disrupt RNF12 function during development or maintenance of specific neuronal populations, leading to intellectual disability." (PMID 33080171, 2020).
melanoma (2 papers, 2022 to 2025). A malignant, usually aggressive tumor composed of atypical, neoplastic melanocytes. "We analyzed single-cell RNA sequencing data of melanoma patient cohorts and found that SRPK2 expression in melanoma cells is associated with poor prognosis." (PMID 36212152, 2022). "To investigate the expression of SRPK1 and SRPK2 in human melanoma at single-cell resolution, we analyzed a dataset from human melanoma biopsies containing 6,696 cells identified by canonical lineage markers." (PMID 36212152, 2022). "So, our main objective in this work was to evaluate the possible differential roles of SRPK1 and SRPK2 in melanoma." (PMID 36212152, 2022). "The serine/arginine protein kinases 1 and 2 (SRPK1 and SRPK2) are classically related to the control of pre-mRNA splicing through SR protein phosphorylation and have been found overexpressed in many types of cancer, including melanoma." (PMID 36212152, 2022). "As selective SRPK pharmacological inhibitors are still unknown, the role of SRPK1 or SRPK2 activity in melanoma remains obscure." (PMID 36212152, 2022). "Interestingly, this cluster of malignant melanoma cells exhibited higher levels of SRPK2 than SRPK1." (PMID 36212152, 2022). "As the used compounds could target at least both SRPK1 and SRPK2, here we sought to obtain additional clues regarding the involvement of these paralogs in melanoma progression." (PMID 36212152, 2022). "Finally, the more prominent impact of SRPK2 genetic targeting in impairing the development of murine melanoma in comparison to SRPK1 suggests that selective SRPK2 inhibition may be considered in further drug discovery efforts." (PMID 36212152, 2022). "This study aims to determine the clinical relevance of SRPK1 and SRPK2 expression regarding dataset analysis before examining the effects of SRPK inhibitors, SRPIN340 and SPHINX31, on cell viability and growth in the melanoma cell lines, A375 and MNT-1." (PMID 41403742, 2025). "However, as SRPIN340 inhibits SRPK1 and to a lesser extent SRPK2, as well other splicing kinases, these data are limited in informing which SRPK1/2 member is relevant for melanoma progression." (PMID 36212152, 2022). "In further in vivo experiments, genetic targeting of SRPK2, but not SRPK1, reduced tumor progression in both subcutaneous and caudal vein melanoma induction models." (PMID 36212152, 2022). "Consistently, genetic targeting of SRPK2, but not SRPK1, impaired the formation of pulmonary nodules and the development of subcutaneous melanoma in mice." (PMID 36212152, 2022).
non-small cell lung carcinoma (2 papers, 2012 to 2021). A group of at least three distinct histological types of lung cancer, including non-small cell squamous cell carcinoma, adenocarcinoma, and large cell carcinoma. "Downregulation of SRPK2 in non-small cell lung cancer cells prevented the induction of apoptosis following cisplatin treatment, whereas downregulation of SRPK1 increased apoptosis." (PMID 33808326, 2021). "Immunohistochemical analysis of SRPK1 and SRPK2 proteins expression in non-small cell lung cancer according to histological subtype." (PMID 23071587, 2012).
squamous cell lung carcinoma (2 papers, 2012 to 2015). A carcinoma arising from squamous bronchial epithelial cells. "Overexpression of SRPK1 and SRPK2 has also been found in lung tumors samples in percentages as high as 92% and 94% for lung adenocarcinoma and 72% and 68% for squamous cell lung carcinoma, respectively." (PMID 26273588, 2015). "Here, we demonstrate that not only SRSF1 but also SRSF2, SRPK1 and SRPK2 proteins are overexpressed in both adenocarcinoma and squamous cell lung carcinoma." (PMID 23071587, 2012).
acute lymphoblastic leukemia (1 paper, 2015). Leukemia with an acute onset, characterized by the presence of lymphoblasts in the bone marrow and the peripheral blood. "High levels of SRPK2 in some acute myeloid leukemia cell lines and in acute lymphoblastic leukemia specimens have been correlated to cell proliferation through the acinus SR protein hyperphosphorylation and cyclin A1 expression." (PMID 26244849, 2015).
alcoholism (1 paper, 2015). "Of these 6 genes, LPAR1, PSD3, and GNAS are associated with brain-related phenotypes (alcoholism, memory, and brain waves), and LPAR1, PSD3, GNAS, and SRPK2 with eQTLs annotated in GTex or PheGenI in any human tissue (brain regions are not well represented in GTEx)." (PMID 26597164, 2015).
bladder carcinoma (1 paper, 2019). "Gaballah identified candidate genes: PURA, SRPK2, TRAK1, BRD2, and UPF3 in progression and invasiveness of bladder carcinoma based on DEGs acquired by comparing invasive and noninvasive samples by Limma R packages in 2016." (PMID 30723390, 2019).
cognitive decline (1 paper, 2020). "Transgenic mice with SRPK2 mutant that cannot be cleaved by AEP showed the elevated synaptic functions and spatial memory while those have truncated SRPK2 underwent 3R- and 4R-tau imbalance leading to accelerate cognitive decline." (PMID 33224974, 2020).
Cognitive impairment (1 paper, 2019). Abnormal cognition is characterized by deficits in thinking, reasoning, or remembering. "Knocking out miR-369 in 3xTg AD mice aggravated cognitive impairment, promoted hyperphosphorylation of tau, and upregulated Fyn and SRPK2." (PMID 32082134, 2019).
Hepatic steatosis (1 paper, 2025). Steatosis is a term used to denote lipid accumulation within hepatocytes. "SRPK2 activation promotes pathogenic LPIN1 splicing, to the lipogenic lipin‐1β isoform via SRSF10, in alcohol‐associated liver disease; genetic or pharmacological inhibition of SRPK2 reduces hepatic steatosis." (PMID 41399527, 2025).
hepatocellular carcinoma (1 paper, 2020). A malignant tumor that arises from hepatocytes. "In hepatocellular carcinoma, SRPK2 silencing elevated Numb expression, which decreased cell migration and invasion by down-regulating Akt phosphorylation and c-Myc expression." (PMID 31898732, 2020).